ARIH1 (ariadne RBR E3 ubiquitin protein ligase 1)
Description:
E3 ubiquitin-protein ligase, which catalyzes ubiquitination of target proteins together with ubiquitin-conjugating enzyme E2 UBE2L3. Acts as an atypical E3 ubiquitin-protein ligase by working together with cullin-RING ubiquitin ligase (CRL) complexes and initiating ubiquitination of CRL substrates: associates with CRL complexes and specifically mediates addition of the first ubiquitin on CRLs targets. The initial ubiquitin is then elongated by CDC34/UBE2R1 and UBE2R2. E3 ubiquitin-protein ligase activity is activated upon binding to neddylated cullin-RING ubiquitin ligase complexes. Plays a role in protein translation in response to DNA damage by mediating ubiquitination of EIF4E2, the consequences of EIF4E2 ubiquitination are however unclear. According to a report, EIF4E2 ubiquitination leads to promote EIF4E2 cap-binding and protein translation arrest. According to another report EIF4E2 ubiquitination leads to its subsequent degradation. Acts as the ligase involved in ISGylation of EIF4E2. In vitro, controls the degradation of the LINC (LInker of Nucleoskeleton and Cytoskeleton) complex member SUN2 and may therefore have a role in the formation and localization of the LINC complex, and as a consequence, nuclear subcellular localization and nuclear morphology.
Synonyms: ARI; UBCH7BP; HARI; HHARI
Tractability: Small molecule: a structure with a bound ligand is known; it has a high-quality binding pocket. PROTAC: ubiquitination databases record sites on it; its protein half-life has been measured.
Gene: Protein-coding gene on chromosome 15 (72,474,308 to 72,602,987, forward strand). Ensembl gene ENSG00000166233.
Subcellular location: Cytoplasm; Nucleus; Nucleus, Cajal body
Subcellular location (Human Protein Atlas): Nucleoplasm
Pathways (Reactome):
Immune System: ISG15 antiviral mechanism; Modulation of host responses by IFN-stimulated genes; PKR-mediated signaling
Disease: RSV-host interactions
Gene Ontology:
Molecular function: protein binding; ubiquitin conjugating enzyme binding; ubiquitin protein ligase activity; ubiquitin protein ligase binding; ubiquitin-protein transferase activity; zinc ion binding; ISG15 ligase activity; ubiquitin-like protein transferase activity; metal ion binding
Biological process: protein ubiquitination; PKR/eIFalpha signaling; ubiquitin-dependent protein catabolic process
Cellular component: Cul2-RING ubiquitin ligase complex; Cul3-RING ubiquitin ligase complex; Cul4A-RING E3 ubiquitin ligase complex; cytoplasm; Lewy body; nuclear body; nucleoplasm; nucleus; SCF ubiquitin ligase complex; cytosol; ubiquitin ligase complex; Cajal body
Genetic constraint (gnomAD): Loss-of-function variants: 8 observed, 47.75 expected, observed/expected ratio (o/e) 0.17, 90% interval 0.097 to 0.3. The upper end of that interval is the gene's LOEUF score, 0.3, which puts it in group 1 of 6, group 1 being the genes least tolerant of losing a copy. Missense variants: 269 observed, 526.99 expected, observed/expected ratio (o/e) 0.51, 90% interval 0.46 to 0.56. Synonymous variants: 202 observed, 190.53 expected, observed/expected ratio (o/e) 1.06, 90% interval 0.94 to 1.19.
Homologues: Orthologues: chimpanzee ARIH1 (100% identical), macaque ARIH1 (100% identical), guinea pig ARIH1 (99% identical), dog ARIH1 (99% identical), mouse Arih1 (99% identical), rat Arih1 (99% identical), pig ARIH1 (99% identical), tropical clawed frog arih1 (92% identical), zebrafish arih1 (89% identical), zebrafish arih1l (87% identical), rabbit ARIH1 (81% identical), Drosophila melanogaster ari-1 (60% identical), and 5 more. Paralogues in human: ARIH2 (31% identical), ANKIB1 (28% identical), RNF19A (18% identical), RNF19B (15% identical), RNF217 (14% identical), RNF14 (13% identical), RNF144A (12% identical), PRKN (12% identical), RNF144B (11% identical).
Diseases named in the same sentence as ARIH1 in open-access papers:
ARIH1 is named in the same sentence as 27 diseases in open-access papers, as found by Europe PMC text mining. Sharing a sentence is not in itself a finding about the gene and the disease. The quoted sentences say what the papers report.
breast carcinoma (8 papers, 2022 to 2025). "Recent studies have linked ARIH1 to cancer progression and chemoresistance, particularly in breast cancer and other solid tumors." (PMID 40075632, 2025). "Dysregulation of ARIH1 has been associated with the development of cancer, particularly breast cancer and gastric cancer, where it affects the stability of key regulatory proteins involved in tumor suppression and DNA repair." (PMID 39851497, 2025). "This stabilization sensitized breast cancer cells to paclitaxel treatment, leading to reduced cell viability, impaired colony formation, and increased apoptosis in ARIH1-deficient cells." (PMID 40075632, 2025). "ARIH1 mRNA expression was significantly elevated in the high-risk group compared to the low-risk group, further supporting its association with aggressive breast cancer subtypes." (PMID 40075632, 2025). "Clinical datasets suggest that ARIH1 is frequently overexpressed in breast cancer and associated with poor patient outcomes, making it a promising candidate for therapeutic targeting and biomarker development." (PMID 40075632, 2025). "Furthermore, we demonstrated that high ARIH1 expression stratifies breast cancer patients into high-risk groups with poor survival outcomes, highlighting its potential as a prognostic biomarker." (PMID 40075632, 2025). "Further, we evaluated ARIH1 expression in high-risk and low-risk breast cancer groups." (PMID 40075632, 2025). "Moreover, high ARIH1 expression was associated with reduced survival in breast cancer patients." (PMID 35102251, 2022). "In this study, we identify ARIH1, a protein that regulates microtubule stability, as a potential therapeutic target and biomarker in breast cancer." (PMID 40075632, 2025). "As a result, breast cancer cells with reduced ARIH1 levels become more sensitive to paclitaxel, leading to greater cancer cell death." (PMID 40075632, 2025). "This positions ARIH1 as a potential therapeutic target to overcome chemoresistance in breast cancer." (PMID 40075632, 2025). "The same group demonstrated that cisplatin treatment of 4T1-derived murine breast cancer (TNBC) led to upregulation of ARIH1." (PMID 39851497, 2025). "In this study, we investigated the role of ARIH1 in regulating microtubule dynamics and its impact on breast cancer cell response to paclitaxel." (PMID 40075632, 2025). "The survival analysis indicated that the higher expression of ARIH1, SIAH1, and UBR5 was associated with shorter OS in breast cancer patients, whereas the higher expression of SIAH2 correlated with prolonged survival." (PMID 40004017, 2025). "We first explored the role of ARIH1 in breast cancer by examining its expression in breast cancer tissue compared to normal breast tissue." (PMID 40075632, 2025). "This study provides a strong rationale for targeting ARIH1 to overcome paclitaxel resistance and improve treatment outcomes in breast cancer." (PMID 40075632, 2025). "Collectively, our findings support ARIH1 as a critical regulator of microtubule dynamics and a promising therapeutic target for enhancing paclitaxel efficacy in breast cancer treatment." (PMID 40075632, 2025). "Functional studies were conducted in breast cancer cell lines to evaluate the impact of ARIH1 depletion on microtubule stability, MAP4 regulation, and paclitaxel sensitivity." (PMID 40075632, 2025). "Ring finger protein 31 (RNF31, also named HOIP), Ran Bp-type and C3HC4-type zinc finger-containing protein 1 (RBCK1), and Ariadne homolog 1 (ARIH1) are members of RBR E3 ligases that are up-regulated in breast cancer." (PMID 35216622, 2022). "ARIH1 silencing in breast cancer cells significantly attenuated cancer cell stemness in vitro and tumor formation in vivo." (PMID 35102251, 2022). "In support of a link between ARIH1 expression and EMT induction, analysis of human breast cancer proteome data revealed an inverse correlation between ARIH1 protein levels and levels of the epithelial markers E-cadherin and Occludin." (PMID 35102251, 2022).
breast carcinoma (continued). "As hnRNP E1 is a known regulator of EMT and cancer progression, we tested the contribution of hnRNP E1 to the ARIH1 KD phenotype in our breast cancer model." (PMID 35102251, 2022). "An increase in ARIH1 expression was observed in cells isolated from lung metastases, compared to mammary tumors from PyMT mice." (PMID 35102251, 2022). "To further interrogate ARIH1 expression in this model, we performed immunohistochemistry on five matched mammary tumor and lung specimens." (PMID 35102251, 2022). "ARIH1 promotes anti-tumor immunity by targeting PD-L1 for proteasomal degradation in breast cancer." (PMID 40004017, 2025). "ARIH1 suppression enhances paclitaxel sensitivity, highlighting its potential as both a therapeutic target and a biomarker for predicting treatment response and patient outcomes in breast cancer." (PMID 40075632, 2025). "By targeting ARIH1, we may improve the effectiveness of microtubule-stabilizing drugs in breast cancer treatment." (PMID 40075632, 2025). "ARIH1 may facilitate the removal of damaged mitochondria to protect breast cancer cells from chemotherapy-induced death." (PMID 35216622, 2022). "We next wanted to test the effect of ARIH1 modulation in breast cancer cells." (PMID 35102251, 2022). "Finally, to investigate ARIH1’s role in human breast cancer, we interrogated data from the Clinical Proteomic Tumor Analysis Consortium (CPTAC) using the UALCAN platform." (PMID 35102251, 2022). "Given that paclitaxel exhibited a greater microtubule-stabilizing effect in ARIH1-deficient cells, we hypothesized that breast cancer cells lacking ARIH1 would demonstrate increased sensitivity and responsiveness to the cytotoxic effects of paclitaxel." (PMID 40075632, 2025). "To further characterize the role of ARIH1 in cancer progression in vivo, we utilized the MMTV-PyVT (PyMT) mouse model of breast cancer." (PMID 35102251, 2022). "In addition, ARIH1 (or HHARI) known as a ubiquitin-protein ligase, contributed to EMT induction and breast cancer progression." (PMID 36119068, 2022). "ARIH1’s function in tumorigenesis does not appear to be limited to breast cancer." (PMID 35102251, 2022).
lung adenocarcinoma (6 papers, 2020 to 2025). A carcinoma that arises from the lung and is characterized by the presence of malignant glandular epithelial cells. "For example, ARIH1 is widely expressed in cancer cells, notably in breast and lung adenocarcinomas, where its expression protects against chemotherapy-induced cell death." (PMID 40075632, 2025). "Suppressed ARIH1 reduced PD-L1 degradation in lung adenocarcinoma biopsies, contributing to cancer escape from anti-tumor immunity." (PMID 37429863, 2023). "A similar increase in ARIH1 protein expression was observed in lung adenocarcinoma samples, with ARIH1 expression significantly correlating with tumor grade." (PMID 35102251, 2022). "The E3 ubiquitin-ligase ARIH1 and not Parkin mediates PINK1-induced mitophagic responses to cisplatin/etoposide in breast and lung adenocarcinomas." (PMID 33280610, 2020).
lung carcinoma (5 papers, 2019 to 2025). "An E3 ubiquitin ligase (ARIH1) that triggers mitophagy protects cells from cisplatin- and etoposide-induced death in lung cancer." (PMID 36289190, 2022). "Although the regulation of mitophagy of cancer cells remains largely unclear, inhibiting specific factors like ARIH1 in lung cancer cells should improve the efficacy and safety of anti-cancer treatment." (PMID 31822748, 2019). "We decided to use A549 lung carcinoma cells, in which mitophagy depends on the endogenous expression of the E3 ligase ARIH1 and does not express Parkin." (PMID 34580273, 2021).
melanoma (4 papers, 2023 to 2025). A malignant, usually aggressive tumor composed of atypical, neoplastic melanocytes. "Small hairpin RNA (shRNA) and genome‐wide CRISPR‐Cas9‐based genetic screenings in melanoma cells, on the other hand, revealed ZNRF3, NF2 and ARIH1 as genes associated with cisplatin resistance." (PMID 40242936, 2025). "ARIH1 (Ariadne1 homolog), another ubiquitin ligase, also enhanced cisplatin resistance in normal and melanoma cells by modulating ARIH1, and the tumor suppressor neurofibrillary protein 2, NF2, enhanced cisplatin resistance in melanoma, but not in normal cells." (PMID 38084101, 2023).
Autoimmunity (2 papers, 2022 to 2024). The occurrence of an immune reaction against the organism's own cells or tissues. "Expectedly, knockout of ARIH1 in myeloid cells fully rescued the autoimmune lethality caused by TREX1 deficiency, suggesting that ARIH1 in myeloid cells sufficiently supports autoimmunity caused by dysfunction of TREX1." (PMID 36217001, 2022). "Here, we show that ariadne RBR E3 ubiquitin protein ligase 1 (ARIH1) catalyzes the mono-ISGylation and induces the oligomerization of cGAS, thereby promoting antiviral immunity and autoimmunity." (PMID 36217001, 2022). "Taken together, these data demonstrate that ARIH1 promotes self-DNA-triggered autoimmunity." (PMID 36217001, 2022). "Ariadne RBR E3 ubiquitin protein ligase 1 (ARIH1, also known as HHARI) promotes antiviral immunity and autoimmunity by inducing ISGylation and oligomerization of cGAS at its K187 residue." (PMID 38970666, 2024).
cervical carcinoma (2 papers, 2021 to 2025). A carcinoma arising from either the exocervical squamous epithelium or the endocervical glandular epithelium. "The increased sample size enabled identification of SMGs previously unreported in cervical carcinoma including NBPF10 (8%), RANBP2 (6%), MSN (6%), KRT8 (6%), POTEC (6%), ZC3H11A (4%), BMS1 (4%), GPX1 (3%), OTOP1 (3%), DNAH12 (2%), COIL (2%), TBC1D26 (2%), SPRED3 (2%), FAM115A (2%), and ARIH1 (1%)." (PMID 34620846, 2021).
colorectal cancer (2 papers, 2022 to 2025). A primary or metastatic malignant neoplasm that affects the colon or rectum. "The RBR E3 ubiquitin ligase ARIH1, which is upregulated in colorectal cancer cells, promotes cell growth and metastasis and correlates with an unfavorable CRC prognosis." (PMID 40285603, 2025). "This study revealed that ARIH1 is upregulated in colorectal cancer (CRC) cells and facilitates cell growth and metastasis." (PMID 40285603, 2025). "Moreover, the effect of ARIH1 silencing on cell invasion was observed in colorectal cancer cells." (PMID 35102251, 2022). "Moreover, ARIH1 protein expression in colorectal cancer patients positively correlated with Vimentin protein expression and negatively correlated with E-cadherin, strengthening the link between ARIH1 and EMT induction in cancer." (PMID 35102251, 2022). "Increased ARIH1 and reduced hnRNP E1 protein levels were detected in the more aggressive HCT116 colorectal cancer cell line, compared to SW480, SW620, and HCT8 cells." (PMID 35102251, 2022).
non-small cell lung carcinoma (2 papers, 2021 to 2023). A group of at least three distinct histological types of lung cancer, including non-small cell squamous cell carcinoma, adenocarcinoma, and large cell carcinoma. "Interestingly, non-small cell lung cancer patients with the ARIH1 missense mutation (E429K) have reduced survival." (PMID 37429863, 2023).
Parkinson's (2 papers, 2012 to 2021). "Conceivably, Ari-1/ARIH1 may become a suitable target for either diagnosis or pharmacological treatment of Parkinson's and related diseases." (PMID 33581113, 2021). "The RBR family of E3 ligases include human E3 ligases such as the human homolog of DrosophilaAriadne (HHARI; also known as ARIH1) that shares homology with Hel1, as well as TRIAD1 (or ARIH2) and Parkin (or PARK2), the latter of which has been implicated in a subset of Parkinson's disease." (PMID 22570702, 2012).
viral infection (2 papers, 2022 to 2023). "All these findings corroborated the observation that ARIH1 up-regulats type I interferon response during virus infection." (PMID 37005687, 2023). "Considering that ARIH1 plays an inhibitory role during H1N1/PR8 infection, we speculated that ARIH1 regulates type I interferon response during virus infection." (PMID 37005687, 2023). "This study also found that viral infection can up-regulate the expression of ARIH1." (PMID 37005687, 2023). "Although it is currently unknown whether there exist additional ISGylated targets of ARIH1 in the context of viral infection, the available data have suggested a positive feedback loop of cGAS ISGylation by ARIH1 to promote antiviral immunity." (PMID 36217001, 2022). "This newly revealed mechanism shows that cellular response increases of ARIH1 and promotes IFN-β expression to boost host survival during viral infection." (PMID 37005687, 2023).
aneurysm (1 paper, 2021). Bulging or ballooning in an area of an artery secondary to arterial wall weakening. "Through literature searches we found that the participant of ubiquitination related proteins (e.g. UCHL1, RNF213, UBR3, ARIH1) in pathogenesis of above-mentioned human aneurysm subtypes (ASH, AAA, CA, AA, AD) has been widely reported before." (PMID 34895131, 2021).
breast tumors (1 paper, 2025). "An analysis of the CPTAC dataset revealed significantly higher ARIH1 protein levels in primary breast tumors (n = 125) compared to normal tissues (n = 18)." (PMID 40075632, 2025).
liver fibrosis (1 paper, 2020). "Indeed, after 6 weeks of CCl4-induced liver fibrosis, we found increased expression of genes encoding several E3 ubiquitin-protein ligases, namely Cbl (Casitas B-lineage lymphoma) and Arih1 (ariadne RBR E3 ubiquitin protein ligase 1)." (PMID 33261190, 2020). "Of relevance, one of the ubiquitin ligases overexpressed in CCl4-induced liver fibrosis, ARIH1, has been previously shown to be a potent mediator of DNA damage-induced translation arrest that protects stem and cancer cells against genotoxic stress." (PMID 33261190, 2020).
lymph node metastasis (1 paper, 2025). "Nonetheless, significant associations were observed between the ARIH1 level and tumor stage (p < 0.001), distant metastasis (p = 0.012), vascular invasion (p = 0.013), and lymph node metastasis (p < 0.001)." (PMID 40285603, 2025).
Obesity (1 paper, 2018). Accumulation of substantial excess body fat. "Instead, our screen suggests that different nearby cis gene may be more fruitful for further functional follow up for obesity, namely ZCCHC8, VPS33A, RSRC2; SPDEF, NUDT3; SETD1, VKORC1; SGSM2, SRR; VASP, SIX5; OTX1; BANK1; ARIH1; ELL; CHST8, respectively." (PMID 29608557, 2018).
Salmonella Infections (1 paper, 2017). Infections with bacteria of the genus SALMONELLA. "Interestingly, ubiquitination of bacteria by ARIH1 is independent of neddylated cullin‐RING ligases; thus, further work is needed to understand the molecular basis of ARIH1 activation during Salmonella infection." (PMID 28821533, 2017).